PRMT3 (protein arginine methyltransferase 3)
Diseases named in the same sentence as PRMT3 in open-access papers (continued):
Sharing a sentence is not in itself a finding about the gene and the disease.
rectal cancer (1 paper, 2025). A primary or metastatic malignant neoplasm that affects the rectum. "To elucidate the molecular mechanisms underlying function of PRMT3 in rectal cancer, we performed a transcriptomic analysis of PRMT3‐KD SW480 cells and CTRL." (PMID 41147802, 2025). "Results showed that PRMT3‐KO also enhanced the sensitivity of rectal cancer to oxaliplatin and irinotecan." (PMID 41147802, 2025). "In pursuit of validating PRMT3's involvement in neoadjuvant chemoradiation resistance in rectal cancer, we generated several rectal cancer patient‐derived organoid lines (PDO) which develops a dense 3D morphology." (PMID 41147802, 2025). "Here, through functional screening, we identify PRMT3 as a key driver of chemoradiotherapy resistance in rectal cancer." (PMID 41147802, 2025). "Through meticulous functional genomic screening, our study has pinpointed PRMT3 as a pivotal contributor to chemoradiotherapy resistance in rectal cancer." (PMID 41147802, 2025). "Given that 5‐FU is just one of the drugs used in neoadjuvant chemotherapy for rectal cancer, we explored whether PRMT3 promoted resistance of rectal cancer to other commonly used drugs." (PMID 41147802, 2025). "In summary, we identify PRMT3 as a key driver of chemoradiotherapy resistance in rectal cancer." (PMID 41147802, 2025). "Conversely, YBX1 is recognized for its transcriptional control over HR repair genes and ABC transporters in cancer, leading us to posit that YBX1, rather than IGF2BP1, is the critical substrate through which PRMT3 regulates chemoradiotherapy resistance in rectal cancer." (PMID 41147802, 2025). "Our data suggest that elevated PRMT3 expression inversely associates with treatment response, overall survival, and progression‐free survival in neoadjuvant settings, positioning PRMT3 as a promising biomarker candidate for tailored neoadjuvant therapies in rectal cancer." (PMID 41147802, 2025).
steatosis (1 paper, 2022). Increased lipid within the cytoplasm of cells. "However, in line with the reduction in hepatic triglyceride accumulation / steatosis upon pharmacological PRMT3 inhibition, lipid droplets were virtually absent in liver sections from SGC707-treated mice." (PMID 35013582, 2022).
tauopathies (1 paper, 2025). "Collectively, this study defines the PRMT3/H4R3me2a/miR‐448 axis as a critical regulatory pathway in tau hyperphosphorylation within PART, underscoring the potential of PRMT3 inhibition as a targeted therapeutic strategy for tauopathies." (PMID 40344412, 2025). "To further explore whether PRMT3 inhibition has potential for treating tau hyperphosphorylation and the resulting neuronal dysfunction, we used PRMT3 specific inhibitor SGC707 to treat in vitro tauopathy cell models induced by okadaic acid (OA)." (PMID 40344412, 2025). "In addition, overexpressing PRMT3 in tauopathy models could potentially exacerbate tau pathology, leading to a faster and more severe progression of disease." (PMID 40344412, 2025). "Treatment with SGC707, a selective PRMT3 inhibitor, effectively reduces tau hyperphosphorylation and demonstrates therapeutic promise for PART and potentially other tauopathies." (PMID 40344412, 2025). "Notably, the PRMT3/H4R3me2a/miR‐448 axis identified in this study provides a novel mechanistic link between epigenetic regulation and tau hyperphosphorylation in PART, and its relevance may extend to other tauopathies, including PSP and CBD." (PMID 40344412, 2025).
tumor (28 papers, 2013 to 2026). "Multiple IF analysis of mouse tumor samples also showed that high expression of PRMT3 was associated with fewer infiltrating CD8+ T cells." (PMID 41129671, 2026). "Our results unambiguously demonstrated that PRMT3‐KO tumors were significantly more susceptible to chemoradiation, as attested by reduced tumor sizes and weights." (PMID 41147802, 2025). "Taken together, our loss- and gain-of-function analyses suggest that PRMT3 is both necessary for and sufficient to promote tumor cell growth in GBM." (PMID 36351894, 2022). "Furthermore, RNA-seq analysis revealed that knockout of PRMT3 downregulates the tumor-associated immune checkpoint, PD-L1, in tumor tissues." (PMID 40050608, 2025). "Also, HCC tumor samples with higher PRMT3 expression had clinicopathologic features associated with more aggressive disease, such as larger tumor sizes, advanced tumor stages, and higher AFP levels." (PMID 39256398, 2024). "PRMT3 deficiency inhibited tumor formation in vivo and prolonged mouse survival." (PMID 36351894, 2022). "• By inhibiting PRMT3 activity, they may provide new therapeutic strategies and potential drug targets for the treatment of diseases associated with PRMT3 abnormalities, such as cardiovascular diseases and tumours." (PMID 41583428, 2025). "Overall, PRMT3 expression was upregulated in EC and might be associated with tumor progression." (PMID 37973560, 2023). "Inhibiting the intrinsic PRMT3 in tumor cells enhances their sensitivity to radiotherapy by suppressing Kyn metabolism." (PMID 41129671, 2026). "In PDX model mice, tumor IDO1 expression in the PRMT3 inhibitor and radiotherapy groups was found to be lower than in the DMSO and radiotherapy groups." (PMID 41129671, 2026). "Flow cytometry analysis of mouse tumor tissues indicated that PRMT3 overexpression hinders the infiltration and functionality of CD8+ T cells after radiotherapy." (PMID 41129671, 2026). "Our study underscores that high intrinsic tumor PRMT3 expression can elevate Kyn metabolism, facilitating the development of radiotherapy resistance." (PMID 41129671, 2026). "In this model, overexpression of PRMT3 significantly accelerated tumor growth in mice undergoing radiotherapy compared with the control group." (PMID 41129671, 2026). "Pharmacologic inhibition of PRMT3 bolsters the efficacy of radiotherapy in suppressing tumor growth, thereby presenting a potential therapeutic strategy for NSCLC." (PMID 41129671, 2026). "In tumor cells, PRMT3 mediated arginine methylation of transcription factor TFAP2A, enhancing its binding to the indoleamine 2,3-dioxygenase 1 (IDO1) promoter." (PMID 41129671, 2026). "Our findings indicate that targeting PRMT3 in tumor cells and inhibiting Kyn metabolism not only suppresses tumor growth but also significantly mitigates the development of an immunosuppressive microenvironment by activating AhR." (PMID 41129671, 2026). "The preferential selection and efficient modification of oncogenic substrates by PRMT3 in the tumor microenvironment are mainly driven by the dual regulation of substrate availability and the post-translational modification of PRMT3 itself." (PMID 41583428, 2025). "To further investigate the effect of PRMT3 on tumor progression, we performed RNA-seq analysis on tumors isolated from Prmt3LKO and Prmt3f/f mice." (PMID 40050608, 2025). "Consistent with the results observed in the Huh7 cell subcutaneous model, Prmt3 overexpression increased tumor growth in both mouse strains." (PMID 40050608, 2025). "Our research establishes a mechanistic link between PRMT3-mediated metabolic reprogramming and tumor immunity." (PMID 40050608, 2025). "The resulting tumor microenvironment promotes M2 macrophage polarization, underscoring PRMT3’s role in metabolic reprogramming and immune evasion." (PMID 41583428, 2025). "The functional plasticity exhibited by PRMT3 underscores the importance of the tumor microenvironment in determining its roles and effects." (PMID 41583428, 2025).
tumor (continued). "Of note, a heatmap based on GSEA showed several tumor-associated immune checkpoints, such as H2-Ab1, CD86, CD80, and CD276, CD274 (Pdl1), were downregulated upon Prmt3 deletion." (PMID 40050608, 2025). "To examine the effect of PRMT3‐KO on the chemoradiation resistance in vivo, we subjected tumor‐bearing mice implanted with PRMT3‐KO and CTRL SW480 cells to chemoradiation treatment." (PMID 41147802, 2025). "In this study, we identified PDHK1, a key regulator of tumor glycolytic adaptation, as a novel substrate of PRMT3 in HCC cells." (PMID 40050608, 2025). "Overall, these results suggest that PRMT3 modulates the tumor microenvironment by regulating PD-L1 expression." (PMID 40050608, 2025). "The diverse substrates and unique structural features of PRMT3 provide key insights into its role in tumours." (PMID 39964832, 2025). "We present a novel metabolic-epigenetic regulatory axis that governs tumor immunity in tumors with high PRMT3 expression." (PMID 40050608, 2025). "These oncogenic interacting proteins are exclusively expressed at high levels in tumors, confining PRMT3’s substrate pool to pro-tumor substrates." (PMID 41583428, 2025). "As expected, Prmt3 overexpression significantly promoted tumor growth, increased tumor weight, and enhanced Ki67 staining, while markedly reducing CD8+ T cell infiltration." (PMID 40050608, 2025). "High PRMT3 levels correlate with advanced tumor stage and aggressive phenotypes, while genetic ablation of PRMT3 suppresses HCC cell proliferation and glycolytic flux." (PMID 41583428, 2025). "Collectively, our data suggest that PRMT3 inhibition activated anti-tumor immunity by impairing HSP60 oligomerization in HCC." (PMID 39256398, 2024). "Collectively, our data suggest that PRMT3-mediated arginine methylation of HSP60 at R446 plays a crucial role in HCC tumor progression and the suppression of T cell infiltration." (PMID 39256398, 2024). "In contrast, the co-expression of PRMT3 with HSP60-WT in PRMT3-KO cells dramatically promoted tumor progression and suppressed T cell infiltration." (PMID 39256398, 2024). "Consistent with our findings from the Prmt3-KO cells, SGC707 delayed tumor progression in both immune-deficient and immune-competent mice, and its effects were more profound in immune-competent mice than in immune-deficient mice." (PMID 39256398, 2024). "We show that PRMT3 expression is induced by ICB-activated T cells via an interferon-gamma (IFNγ)-STAT1 signaling pathway, and higher PRMT3 expression levels correlate with reduced numbers of tumor-infiltrating CD8+ T cells and poorer response to ICB." (PMID 39256398, 2024). "Collectively, our data suggest that PRMT3-mediated methylation of HSP60 at R446 prevents the activation of anti-tumor immunity through the maintenance of mitochondrial integrity and inhibition of cGAS/ STING activation HCC in vitro and in vivo." (PMID 39256398, 2024). "We found that Prmt3 KO dramatically improved the response of tumor-bearing mice to anti-PD1 therapy using the Hepa1-6 model that displays a modest response to anti-PD1 therapy." (PMID 39256398, 2024). "Collectively, these results strongly suggest that the activation of cGAS/STING signaling directly mediated the anti-tumor effects of PRMT3 KO or inhibition through activation of T cell-mediated anti-tumor immunity in HCC." (PMID 39256398, 2024). "To investigate the role of PRMT3 in regulating T cell-mediated anti-tumor immunity, we employed both genetic and pharmacological approaches to determine the effect of Prmt3-KO and PRMT3 inhibition on tumor progression using the Hepa1-6 syngeneic model." (PMID 39256398, 2024). "We found that high PRMT3 expression levels were negatively correlated with the abundance of CD8+ T cells in HCC tumor samples." (PMID 39256398, 2024). "Meanwhile, PRMT3 overexpression promoted tumor proliferation, whereas PRMT3 knockdown inhibited tumor growth in vitro and in vivo." (PMID 39619442, 2024).
tumor (continued). "We then examined the expression of PRMT3 in HCC tumor samples and the corresponding adjacent normal liver tissues." (PMID 39256398, 2024). "Collectively, our data suggest that PRMT3 inhibition activated the anti-tumor immunity through increasing CD4+ and CD8+ T cell infiltration and activating CD8+ T cells." (PMID 39256398, 2024). "Genetic depletion or pharmacological inhibition of PRMT3 elicits an influx of T cells into tumors and reduces tumor size in HCC mouse models." (PMID 39256398, 2024). "The tumor volume and weight of the mice treated with the combination of PRMT3 downregulation and anti‐PD‐1 were further reduced compared to those of the other mice." (PMID 37973560, 2023). "To examine the effect of PRMT3 KO on the response of HCC cells to OXA in vivo, we subjected tumor-bearing mice implanted with PRMT3-KO and -WT PLC-8024 cells to vehicle or OXA treatment." (PMID 37024475, 2023). "PRMT3 knockdown in GSCs induced cell cycle arrest and apoptosis, and its inhibition led to decreased tumor growth in a nude mouse flank model." (PMID 37205197, 2023). "Consistently, qRT‒PCR data showed relatively higher levels of PRMT3 mRNA in fresh EC tumor tissues than in the corresponding adjacent normal tissues." (PMID 37973560, 2023). "Knockdown of PRMT3 increased lipid peroxidation levels in cells and accelerated tumor ferroptosis, all of which inhibited resistance to ferroptosis in EC." (PMID 37973560, 2023). "In the mouse subcutaneous transplantation tumor model, the combination of PRMT3 inhibition with anti‐PD‐1 was observed to have the most beneficial therapeutic impact and resulted in the highest level of ferroptosis in all groups." (PMID 37973560, 2023). "Compared to those in the other three groups, bilateral tumors in the bilateral PRMT3 knockdown tumor combined with the left‐sided radiation therapy group showed stronger antitumor effects and greater ferroptosis." (PMID 37973560, 2023). "Here, a comprehensive analysis of the Cancer Genome Atlas database and Clinical Proteomic Tumor Analysis Consortium database identifies that PRMT3 plays an important role in EC." (PMID 37973560, 2023). "Our loss-and gain-of-function studies demonstrated that PRMT3 is required for GBM cell proliferation, survival, and tumor growth in vitro and in vivo." (PMID 36351894, 2022). "Consistently, stable PRMT3 knockdown strongly inhibited tumor growth in xenograft mouse models, along with a significant decrease in cell proliferation as well as an increase in apoptosis." (PMID 36351894, 2022). "The tumor volumes and weights were significantly reduced in the PRMT3 knockdown groups when compared with controls." (PMID 36351894, 2022). "In in vivo tumour growth assays, the increase in both tumour volume and weight were detected in the group of mice injected with PRMT3‐overexpressing cells, whilst SGC707 treatment reversed this effect." (PMID 35090076, 2022). "Using WST-1 cell viability and proliferation assays, we found that knockdown of PRMT3 resulted in a significant reduction in tumor cell growth and proliferation." (PMID 36351894, 2022). "In contrast to the control group, the mice implanted with PRMT3-depleted GSC 20 cells exhibited a significant decrease in tumor cell growth at Day 70 post-transplantation and a significant extension of lifespan." (PMID 36351894, 2022). "We observed that knockdown of PRMT3 in GSC11 cells inhibited tumor-sphere formation as indicated by a reduction in the sphere size." (PMID 36351894, 2022). "The tumours of mice in PRMT3‐knockdown groups grew more slowly and were smaller than those in the control group, whilst PRMT3 overexpression exhibited the opposite effects." (PMID 35090076, 2022). "The mRNA expression level of PRMT3 was significantly higher in HCC tissues than in corresponding adjacent non‐tumour tissues." (PMID 35090076, 2022). "Analysis showed that silencing of PRMT3 significantly inhibited tumor growth and tumor angiogenesis." (PMID 34753906, 2021).
tumor (continued). "Semi-quantification of the protein level by densitometry demonstrated that tumor tissues have > 2-fold increase of PRMT3 when compared to the averaged level of four adjacent normal tissues." (PMID 31324208, 2019). "Immunohistochemical staining showed that PRMT3 protein is mainly detected in ductal cells and its expression is significantly increased in tumor tissues." (PMID 31324208, 2019). "DAL-1/4.1B, a tumor suppressor, interacts with PRMT3 and suppresses its methyltransferase activity, indicating a potential role of PRMT3 in control of tumor growth." (PMID 31378783, 2019). "In another animal study, depletion of PRMT3 in Miapaca-2 pancreatic cells decreased tumor growth in vivo and increased cancer cell apoptosis in the tumor tissues." (PMID 31324208, 2019). "The expression of PRMT3 and ABCG2 and their association were investigated in PDAC tumor tissues (N = 81) by immunohistochemical staining." (PMID 30577570, 2018). "A number of histone methyltransferases, including Setd3, Setd5, Suv39h2, Smyd3, Prmt3, Prmt6, Nsd1, and Nsd2, were up-regulated in metastases compared to disseminated tumor cells or primary tumors." (PMID 23520493, 2013). "Interestingly, the subcutaneous tumor model in BALB/c nude mice demonstrated a less pronounced impact of PRMT3 overexpression on tumor growth compared with the model in C57BL/6 mice." (PMID 41129671, 2026). "Additionally, PRMT3’s regulatory influence on the tumor-immune microenvironment suggests its potential in radiotherapy combined with immunotherapy." (PMID 41129671, 2026). "Consequently, in tumor cells with upregulated PRMT3, IDO1 transcription is enhanced, thereby activating Kyn metabolism." (PMID 41129671, 2026). "Data analysis from TCGA supports this hypothesis, showing that PRMT3 is inversely correlated with T-cell infiltration across various tumor types, including LUSC and LUAD." (PMID 41129671, 2026). "In tumor tissues, PRMT3 mainly interacts with oncogenic signaling molecules." (PMID 41583428, 2025). "By keeping this pathway in check, PRMT3 may allow tumors to escape immune surveillance, promoting an environment conducive to tumor growth and metastasis." (PMID 41583428, 2025). "Also, we found that KDM4A‐KO significantly diminished the effect of PRMT3‐OE on cell apoptosis, γH2AX accumulation and tumor growth." (PMID 41147802, 2025). "There is a potential role for PRMT3 in the control of tumor growth and disease development." (PMID 41154773, 2025). "We then validated the regulation of Prmt3 on these checkpoint molecules in tumor tissues." (PMID 40050608, 2025). "JX06 treatment also attenuated the tumor-promoting role of PRMT3 in HCC in vitro and in vivo." (PMID 40050608, 2025). "Furthermore, in Huh7 xenograft mouse model, JX06 treatment diminished the tumor-promoting effects of PRMT3." (PMID 40050608, 2025). "Notably, JX06 treatment effectively blocked the tumor-promoting effects of Prmt3 in nude mice, and exhibited a more pronounced inhibition in C57BL/6 mice." (PMID 40050608, 2025). "Additionally, in patient‐derived xenograft (PDX) model harboring high PRMT3 expression, while acipimox or chemoradiation alone had limited impact, their combination elicited substantial tumor regression." (PMID 41147802, 2025). "Conversely, in a microenvironment characterized by heightened immune pressure, PRMT3 may pivot toward enhancing immune evasion strategies through c-MYC stabilization or other tumor-promoting pathways." (PMID 41583428, 2025). "Anti-PD-L1 treatment reversed PRMT3-induced tumor growth and restored CD8+ T cell infiltration." (PMID 40050608, 2025). "Our analysis of pan-cancer data from TCGA reveals a positive correlation between PRMT3 and PD-L1 expression across various tumor types, suggesting that the PRMT3-lactate-PD-L1 regulatory axis may be a common mechanism in different cancers." (PMID 40050608, 2025).